NOTCH1 (notch receptor 1)
Diseases named in the same sentence as NOTCH1 in open-access papers (continued):
Sharing a sentence is not in itself a finding about the gene and the disease.
tumor (continued). "Targeting the notch pathway using Notch1 specific antibodies has also been shown to have similar anti-angiogenic and anti-tumour effects in two different xenograft models." (PMID 26620208, 2016). "The Notch ligands JAG1 and Dll4 and the Notch receptors Notch1–4 are functionally overexpressed in KS tumor cells." (PMID 27760204, 2016). "Herein, we show that the macrophage-induced invadopodium is formed through a Notch1/MenaINV signaling pathway in the tumor cell upon macrophage contact." (PMID 27901093, 2016). "Even though NOTCH1 is one of the most frequently mutated genes in HNSCC, there are contradictory studies about its influence on tumor development." (PMID 27596625, 2016). "For example, loss of chromosome 9q34 removes tumor suppresser genes TSC1 (an mTOR pathway inhibitor), NOTCH1 (a development and stemness regulator), and GRIN1 (a calcium regulating tumor suppressor)." (PMID 27391266, 2016). "In these mice, Notch1 ablation resulted in decreased levels of the Notch target gene expression and of pERK1/2, resulting in reduced tumor formation, while Notch2 ablation showed an increase in HES1 expression and resulted in increased carcinogenesis." (PMID 26713603, 2016). "In our previous study, we confirmed that miR-34a suppressed NOTCH1 expression, leading to inhibition of tumor formation in nude mice." (PMID 26895471, 2016). "Decreased Notch1 total staining in tumor xenografts after treatment with higher doses of CO suggests cleavage and activation of Notch1 signaling which is characteristic of M1 macrophage skewing." (PMID 26993595, 2016). "It was also clear that the activation of Notch1 was restricted to the tumor compartment as the surrounding stromal tissue stained negatively for NICD1 (arrow)." (PMID 27491826, 2016). "Overexpression of Notch1 and Notch3 has been associated with increased risk of lymph node metastasis and advanced TNM (tumor size, lymph nodes, and metastases) stages." (PMID 27847554, 2016). "An in vivo study also demonstrated that overexpression of NOTCH1 ablated the inhibitory effects of miR-139-5p on tumor growth." (PMID 27738333, 2016). "Our result showed that tumor lesions in HBV-infected HCC have increased level of Notch1 (50%), Dll4 (62.5%), and Jagged1 (12.5%), compared to non-tumor lesions." (PMID 26766040, 2016). "We sought to determine if macrophage – induced Notch1 signaling in tumor cells results in expression changes in genes with known roles in invadopodium formation and function." (PMID 27901093, 2016). "Some reports also suggested NOTCH1 regulatory mechanisms by some tumor-suppressive miRNAs, such as miR-34 family, miR-124 and miR-935." (PMID 27938406, 2016). "Among the predicted targets, we chose to further investigate NOTCH1 because of its importance in tumorigenesis, tumor progression and stem cell maintenance." (PMID 27738333, 2016). "In this study, we aimed to understand the molecular mechanisms governing RKIP-dependent Notch1 activation in tumor progression using overexpression or knockdown of RKIP in cancer cells." (PMID 26716415, 2016). "To further elucidate the role of Notch1 and Erk1/2 signaling and the regulatory role of HO-1 in the tumor microenvironment, we performed an ELISPOT assay in which we identified HO-1 interacting proteins." (PMID 26993595, 2016). "There was a report suggesting that NOTCH1 functions in endothelial progenitor cells to initiate tumor vasculogenesis in HCC." (PMID 27938406, 2016). "To confirm that the increase in MenaINV mRNA is regulated by the macrophage-tumor cell contact initiated Notch1 signaling, we treated the tumor cells with Notch1 siRNA or DAPT." (PMID 27901093, 2016).
tumor (continued). "For example, Notch1 is an oncogene in most systems, but in skin, some squamous epithelia, vasculature, and potentially NETs, it behaves as a tumor suppressor." (PMID 27148486, 2016). "In conclusion, our study showed that Notch1 induced CD133 expression through RBP-Jκ dependent pathway, and Notch1 played a critical role in the tumor progression of diffuse type gastric cancers." (PMID 27489358, 2016). "In glioma, miR-34 was shown to inhibit tumor growth in vivo by down-regulating Notch1 and Notch2 expression." (PMID 26713603, 2016). "NOTCH1 activation contributed to tumor cell growth and proliferation while NOTCH1 down-regulation inhibited the invasion and migration by inactivating the Cox-2/Snail/E-cadherin pathway or through regulation of PTEN and FAK." (PMID 27938406, 2016). "The bidirectional link between NOTCH1 and NF-κB is well known, indicating a promotion of tumor cells upon NOTCH1 activation." (PMID 27566587, 2016). "To explore the role of Notch1 signaling in determining the tumor regulatory function of MSC-DF, we first generated MSC-DF expressing N1IC." (PMID 27813493, 2016). "Soluble versions of the Notch1 receptor have also been developed, utilising the whole of the Notch1 ECD fused to an Fc tag (Notch1 decoy) this had anti-angiogenic effects in mouse tumour xenografts." (PMID 26620208, 2016). "The Notch ligands JAG1 and Dll4, and the Notch receptors Notch1–4 are highly expressed in KS tumor cells." (PMID 27760204, 2016). "One of the goals of this study was to identify serum biomarkers of propensity towards tumor response to Notch1 inhibitors as well as of indicators of treatment efficacy." (PMID 27167202, 2016). "For instance, constitutively activating mutations in Notch1 and Notch2 are equally oncogenic in a subset of triple negative breast cancer (TNBC), despite the fact that Notch2 has been described as a tumor suppressor in TNBC cell lines." (PMID 27148486, 2016). "Since the overt tumors cannot be considered as early lesions, we assessed the contribution of Notch1 to the “field effect” of non-tumor liver tissue." (PMID 27167202, 2016). "In conclusion, in this study we showed that Notch1 expression correlates with both tumor development and recurrence making Notch1 a good candidate for targeted therapies in HCC." (PMID 27167202, 2016). "By using HNSCC xenograft model, we further demonstrated that inhibition of NOTCH1 signaling by γ-secretase inhibitor (GSIs) DAPT is efficacious in downsizing tumor growth and reducing CSCs in HNSCC." (PMID 27108536, 2016). "Notch1 and MenaINV expression are required for tumor cell transendothelial migration, a necessary step during intravasation." (PMID 27901093, 2016). "We found that Notch1 is required for transendothelial migration of tumor cells and dissemination of tumor cells from the primary tumor." (PMID 27901093, 2016). "Our finding that absence of Trib2 promoted Notch-induced T-ALL was surprising as TRIB2 expression correlates with activated NOTCH1 in primary patient tumor samples." (PMID 27191957, 2016). "Treatment with the Pim inhibitor DHPCC-9 efficiently blocks the tumor-promoting effects of Notch1, and vice versa, the γ-secretase inhibitor DAPT abrogates the tumor-promoting effects of Pim1." (PMID 27281612, 2016). "To elucidate the mechanism(s) for the Notch1-determined tumor-regulating role of MSC-DF, we conducted cDNA microarray analyses to identify the putative target genes of Notch1 signaling in MSC-DF." (PMID 27813493, 2016). "We have recently demonstrated a crucial role for Notch1 signaling in governing the tumor-regulating function of CAF." (PMID 27813493, 2016). "Notch1 expression was upregulated in tumor samples and inversely correlated with expression of miR-139-5p." (PMID 27738333, 2016).
tumor (continued). "In an effort to bring scientific knowledge from the bench to the bedside, several anti-Notch1 agents are under investigation and it's of important interest to identify molecular biomarkers that can be used to predict tumor response or resistance to therapy." (PMID 27167202, 2016). "Reduced levels of NICD1 and Notch1 target genes, such as Skp2, c-Myc and Hes1, confirmed that PF-03084014 efficiently reached the target in Ptenpc−/− tumours." (PMID 27941799, 2016). "On the other hand, Huntzicker and coauthors described how Notch1 inhibition altered the proportion of tumor types, reducing HCC-like tumors and increasing cholangiocarcinoma-like tumors." (PMID 28036048, 2016). "These antibodies are able to target cancers by inhibiting simultaneously cancer cell growth and by disrupting tumor angiogenesis that depends on DLL4/Notch1 signaling." (PMID 26713603, 2016). "Elevated NOTCH1 protein was mainly located in the carcinoma nest area and middle differentiation districts in tumor sample, whereas low expression was observed in the basal layer or sporadically distributed in reticular layer." (PMID 27108536, 2016). "These spheroid ovarian CSCs showed elevated levels of the CSC marker proteins CD44 and CD117, as well as increased Notch1 mRNA levels when compared to parental bulk tumor cells." (PMID 27626163, 2016). "R26PR-derived tumors and tumor cell lines overexpress NOTCH1 and are sensitive to pharmacological inhibition of NOTCH1 protein processing." (PMID 27106930, 2016). "The mRNA levels of pluripotency genes, Nanog and SOX-2, tumorsphere formation ability, tumor growth, and lung metastasis of SC-M1 cells were elevated by activated Notch1 pathway through miR-151-5p." (PMID 27191259, 2016). "One study showed that stable bone microvasculature maintained a dormant niche by promoting tumour cell quiescence through Notch-1-mediated regulation of neovascular tips and the angiocrine tumour suppressor functions of thrombospondin-1 (TSP-1)." (PMID 27782035, 2016). "We show that inhibition of Pim-mediated phosphorylation of Notch1 efficiently reduces tumor growth, and that simultaneous inhibition of Notch and Pim is even more effective." (PMID 27281612, 2016). "This is supported by experimental evidence in a range of cells of different tumor origin, either subjected to Notch1 genetic silencing or treated with gamma secretase inhibitors to block this signaling cascade." (PMID 27749937, 2016). "In contrast with the role of Notch1 in promoting tumor initiation and progression, Notch2 shows a tumor suppressive activity by mediating cell differentiation in lung carcinogenesis." (PMID 27847554, 2016). "Here we show that the expression of the MenaINV isoform is induced by activation of Notch1 signaling in tumor cells." (PMID 27901093, 2016). "This interpretation is consistent with the functional studies of the role of NOTCH1 in ESCC cells, as NOTCH1 depletion promotes tumor cell proliferation in tissue culture." (PMID 26528858, 2016). "We show that these events require the Notch1 receptor on the tumor cell and that Notch1 signaling induces MenaINV expression via activation of transcription." (PMID 27901093, 2016). "In the presence of estradiol, wild-type Notch1 and the SE mutant both enhanced tumor growth, while the SA mutant strongly suppressed it." (PMID 27281612, 2016). "Consistently, a tumor-suppressive role for NOTCH1 in ESCC was supported by MTT assay in KYSE150 and KYSE140 cells." (PMID 26528858, 2016). "On the other hand, Notch1 and 2 were reported to play important roles in tumor proliferation and invasion in IHCC cell lines." (PMID 27821106, 2016). "To note, NOTCH1 mutations in SqCC appeared to be more frequent than pulmonary adenocarcinoma, and their typical location in close proximity of the ligand-binding domain leads to the speculation that Notch1 is more likely to function as a tumor suppressor in SqCC than in the adenocarcinoma histology." (PMID 27847554, 2016).
tumor (continued). "Our previous work showed that Notch1 intracellular domain (NICD) protein is overexpressed in GC tissues and is associated with overall patient survival, tumour metastasis and an advanced tumour stage 17." (PMID 26612211, 2016). "Enhanced NOTCH1 was correlated with progression, tumor grade and metastasis resulting from apoptosis inhibition." (PMID 27938406, 2016). "Notch1 signalling contributes to tumour progression characteristics (e.g., invasion, EMT, metastasis, and angiogenesis)." (PMID 27323817, 2016). "Beside ALDH1A1 and SOX2, other molecules such as DKK1 and NOTCH1 were notably upregulated in CSCs during tumor progression." (PMID 27292183, 2016). "Nonetheless, this notion was very quickly challenged following contradicting observations in solid tumors, in which NOTCH1 seemed to act as a tumor-suppressor." (PMID 25836654, 2015). "In order to assess the relevance of MRP1 expression and Notch signalling in chemotherapy treatment, the expression levels of MRP1 and activated Notch1, Notch1IC, were examined using immunohistochemistry in tumours from 29 breast patients treated with NAC." (PMID 26362310, 2015). "In the subgroup of neoadjuvantly treated GC patients, we identified only a trend toward an association of a higher NOTCH1 and NOTCH2 expression in the pretherapeutic biopsies and worse tumor regression after chemotherapy." (PMID 25954607, 2015). "Here, we demonstrated that tetrandrine had notable effects on NB4 tumor growth repression, including the induction of cell cycle arrest, autophagy, differentiation, ROS accumulation, and Notch1 signaling activation, not only in vitro but also in vivo." (PMID 25797266, 2015). "Notch1 functions as either a tumor suppressor gene or an oncogene in many human carcinomas, which is cell type-specific." (PMID 25887589, 2015). "It was reported that Notch1 acted as a tumor suppressor in medullary thyroid carcinoma (MTC), and activation of Notch1 inhibited growth of MTC cells and induced apoptosis of MTC cells." (PMID 25887589, 2015). "It thus opens a new avenue to target TME by either reprograming and converting CAF from ‘tumor promoters’ to ‘tumor suppressors’ through therapeutic activation of Notch1 pathway or directly exploiting Notch downstream mediator(s), i.e. WISP1." (PMID 26562315, 2015). "Results showed that EGFR inhibitors at clinically relevant doses can reduce the regulation of HIF-1α and Notch1 in this tumor type with limited side effects." (PMID 25723392, 2015). "In our MT model, Notch1 transcription is elevated in jnk2ko tumors in concordance with elevated portions of CK8/18+ tumor cells, suggesting a stronger influence on luminal cell populations." (PMID 25970777, 2015). "A significant upregulation of protein levels of Notch1 and Notch2 receptors, and Hes1 and Hey1 products was observed in bortezomib-treated group when compared with tumor alone group." (PMID 26431276, 2015). "In the context of heterogeneous Notch1 activation, we observed a heterogeneous Ki67 labeling/tumor cell proliferation." (PMID 25653136, 2015). "MYH9, 10 and 14 mutant tumors also exhibited mutational inactivation and/or copy loss of commonly altered tumor suppressors CDKN2A (p16), FAT1, or NOTCH1, and infrequently altered TGFβ pathway components, TGF-B-R2 or SMAD4." (PMID 26369831, 2015). "Detectable tumor Notch1, predominantly localized to the membrane and cytoplasm, was observed in 29 cases (50%, 95% Blyth-Still-Casella confidence interval 37 – 63%)." (PMID 25653136, 2015). "Previous reports suggested that the interaction between HIF-1α and Notch1 can influence tumor angiogenesis." (PMID 25723392, 2015). "Treatment with the Notch1 antibody resulted in decreased rates of tumorigenesis and tumor recurrence, demonstrating the potent antitumor efficacy of a Notch1 antibody and remarkable activity against CSCs." (PMID 26121683, 2015). "In the control group, the expression of Notch1 was detected with a variable degree of intensity in most of the tumor cells." (PMID 25879451, 2015).
tumor (continued). "Taken together, combined targeting of Notch1 and proteasome by GSI-I and BTZ, respectively, causes synergistic tumor suppression of T-LPN." (PMID 25879451, 2015). "Further, combinatorial treatment of MAb and Doxorubucin of HCT-116 xenografts resulted in significant regression of the pre-formed tumor validating the effectiveness for Notch1 MAb in adjuvant chemotherapy." (PMID 26046801, 2015). "There were a total of 13 references that assessed the correlation between Notch1 expression and tumor clinicopathological parameters." (PMID 25996086, 2015). "CQ normalized tumor vessel structure and perfusion function, improved hypoxia, and reduced tumor invasion through endosomal Notch 1 trafficking and signaling in endothelial cells." (PMID 25944689, 2015). "RNA expression analysis detected increased expression of MET and NOTCH1 compared to both normal controls and tumor expression data from a range of malignancies publicly available from The Cancer Genome Atlas (TCGA)." (PMID 25798586, 2015). "Among the most prominent genes, NOTCH1 has been suggested to be able to act both as a tumor-suppressor regulating cell squamous differentiation and as an oncogene promoting EMT." (PMID 25836654, 2015). "Some oncogenic pathways can attenuate TGF-β mediated tumor suppressor function, such as Notch1 and c-Myc." (PMID 26356817, 2015). "Our results defined Notch1 signaling as a molecular switch controlling tumor-regulating function of CAF." (PMID 26562315, 2015). "The five CLIC loci that co-localize with the Notch1 locus collectively harbour insertions in 63 independent tumour samples." (PMID 25721899, 2015). "Different and partly opposite roles in one tumor entity have been found for NOTCH1 and NOTCH2, indicating specific functions of the two receptors." (PMID 25954607, 2015). "In fact, in vitro the restoration of these miRNA levels down-regulated Bcl-2 and Notch1/2 stemness genes and reduced in vitro the inhibition of tumor sphere (tumor stem cell colonies) formation reducing tumor growth in pancreatic cancer cell engraftment." (PMID 26259238, 2015). "A number of studies have shown that the activation of Notch1 signaling promotes p21 expression in certain types of tumor cells, but inhibits p21 expression in other types." (PMID 24396472, 2014). "These spheroid ovarian CSCs also showed elevated levels of the CSC marker proteins CD44 and CD117 as well as an increase in mRNA levels of Notch1 and other stem cell genes, compared with differentiated cells and parental bulk tumor cells." (PMID 25366565, 2014). "For instance, nanoparticle (NP) technology has been applied to deliver specific siRNA to knockdown Notch1 to arrest tumor growth and reverse EMT by the up-regulation of miR-200a and down-regulation of the transcription factors ZEB1, ZEB2, Snail and Slug." (PMID 25477004, 2014). "In particular, it has been shown that the sequestering of mRNA Notch1 by the tumor suppressor microRNA miR-34a drives cells with Notch signal bimodality." (PMID 24781918, 2014). "According to the results of the western blot analysis, the expression of Notch1 was significantly upregulated in the tumor tissues compared with the adjacent normal mucosa tissues." (PMID 24932308, 2014). "Subsequently, N1IC protein levels was decreasing, and repressed the expression of Notch1 target genes, eventually enhanced tumor neovascularization and promoted lung tumor growth." (PMID 25420528, 2014). "Studies have indicated that PDGFD promoted cell proliferation by increasing DNA binding capacity of NF-κB and down-regulation of PDGFD inhibit tumor invasion through inactivation of Notch-1 and NF-κB signaling." (PMID 25108500, 2014). "Microarray analysis discovered that the expression levels of Notch1, and its target Hes1, increased with increasing tumor grade." (PMID 25309874, 2014). "Nevertheless, mislocalization of Fbw7 by CRM1 over-expression results in Notch1 nuclear accumulation and consequent activation of tumor promoting pathways." (PMID 24899509, 2014).